ISG15 (ISG15 ubiquitin like modifier)
Diseases named in the same sentence as ISG15 in open-access papers (continued):
Sharing a sentence is not in itself a finding about the gene and the disease.
infection (continued). "Finally, after 24 h of infection, the IAV-induced expression of ISG15 polypeptide in NAA60-depleted cells was further increased by a significant 4.3-fold (P=0.016) compared to control cells." (PMID 35095845, 2021). "This strategy allowed us to detect three genes, namely BAFT, ISG15 and DNMT1, that clearly differentiate groups of infection with high accuracy (training set: area under the curve (AUC) 0.86 (sensitivity: 0.81; specificity: 0.87); testing set: AUC 0.87 (sensitivity: 0.82; specificity: 0.86))." (PMID 33808774, 2021). "However, many of these studies relied on artificial systems that used ectopic overexpression of ISG15 in cultured cells, leading to overexpression artefacts, and on treatment with IFNs which could induce a stronger ISGylation response than what is physiologically induced during infection." (PMID 34447387, 2021). "However, at 12 h after infection, the expression of IFN1, ISG15, and Mx in rVHSV-P-infected cells increased to levels similar to those in rVHSV-wild-infected cells." (PMID 33465148, 2021). "However, the interferon response (IFNβ1, CXCL10, ISG15, MX1 and MX2) was delayed and increased at 48 h post-infection." (PMID 34452468, 2021). "In this study, we demonstrated that infection with A12-Lpro W105A also disrupted efficient DUB activity, suggesting that Ub and ISG15 may have overlapping target-binding profiles." (PMID 32295921, 2020). "Our main findings were: 1) the host immune response was initiated only in fetuses with detectable levels of PRRSV; 2) upon infection of fetal thymus, a set of core responsive IFN-inducible genes (CXCL10, IFIH1, IFIT1, IFIT3, ISG15, and MX1) were strongly upregulated in both tissues." (PMID 33148169, 2020). "While we did not observe any significant differences in p24 infection, it is possible that lower levels of ISG15 activity resulted in reduced chemoattraction and stimulation of CD4+ cells." (PMID 33080839, 2020). "Because both ISG15 and USP18 regulate the type I IFN signaling pathway, we evaluated Mx1 (another ISG) expression in ISG15-knockdown cells and USP18-knockdown cells following IFN-α pretreatment and subsequent infection with CSFV." (PMID 32093773, 2020). "As a control, cell lysates were evaluated by Western blot analysis for the presence of ISG15 and ISGylated proteins prior to infection (data not shown)." (PMID 32295921, 2020). "Expression of ISG15 and RSAD2 displayed a sharp time-dependent increase following ORFV infection." (PMID 31963559, 2020). "Furthermore, the expression levels of IFN 1, PKR, MXa, and ISG15 were significantly downregulated and upregulated by miR-202-5p mimics or miR-202-5p inhibitor in ZBE3 cells compared to the control group post RGNNV infection, respectively." (PMID 32120903, 2020). "Analysis of IFN-β and ISG15 transcript levels during infection in the presence and absence of ruxolitinib confirmed the ability of the drug to inhibit IFN signaling and ISG induction, but not the induction of IFN itself." (PMID 31671153, 2019). "This is because in the absence of infection, ISG15 plays a role in the maintenance of mitochondrial homeostasis." (PMID 31921100, 2019). "In orange-spotted grouper (Epinephelus coioides) spleen cell line (GS), ISG15 was not significantly upregulated by Singapore grouper iridovirus (SGIV) infection, while it was overexpressed by grouper nervous necrosis virus (GNNV)." (PMID 30886611, 2019). "Infection with either HCMV or UV-HCMV potently upregulated ISG15 in the primary HFs and in V/HFs but not in the nPro/HFs." (PMID 30871003, 2019). "Consequently, for the proteomics analysis, we infected Isg15−/−, wild-type, and USP18 C61A/C61A mice via intravenous injection and harvested liver tissue following 72 h of infection." (PMID 31772204, 2019).
infection (continued). "We show that the expression of the interferon-stimulated proteins MX1, IFIT1, IFIT3 and ISG15, as well as expression of defense response proteins DDX58, STAT1, OAS3, EIF2AK2 and SAMHD1 was significantly up-regulated in these cells upon infection with either virus." (PMID 30959732, 2019). "However, during infection with VACV, ISG15, which is strongly induced in a T1-IFN-independent manner in infected skin, controls mitochondrial function and limits virus replication within infected cells." (PMID 31603920, 2019). "Although Usp18-/- mice exhibited less replication of LCMV and VSV, ISG15- or Ube1L-knockout mice had the same sensitivity to LCMV and VSV infection as wild-type mice, indicating that USP18 may behave in an ISG15-independent manner." (PMID 31871427, 2019). "These nPro/HFs and V/HFs were recently utilized, alongside IRF3 KO CRISPR/Cas9 HFs, to demonstrate that expression of viperin, ISG15, IFIT1, IFIT2, IFIT3, Mx1, and Mx2 mRNA during infection with HCMV can be induced in an IRF3-dependent, STAT1-independent manner." (PMID 31921100, 2019). "Induction of the IFN I pathway after infection with the wt isolate was also evidenced by the upregulation of several interferon-induced proteins (IFIT-I, ISG15, and IFI44) in head kidney and nervous tissue, and some exclusively in head kidney (GIG1 and interferon-induced very large GTPase 1)." (PMID 30065724, 2018). "To compare the viruses' abilities to limit the establishment of an antiviral state, we infected equine cells (multiplicity of infection [MOI], 0.1) with each of the viruses and monitored the expression of two ISGs (ISG15 and MX1) by Western blotting at different times postinfection." (PMID 29237841, 2018). "We unequivocally show that ISG15 production during Toxoplasma infection results in the recruitment of CD8α+ dendritic cells (DCs) to the site of infection and that ISG15 exclusively stimulates IL-1β and not IL-12 production by CD8α+ DCs." (PMID 29891555, 2018). "We then confirmed that knockdown of the CD147 expression by miR-US25-1-5p could specifically reduce the activation of IFNB1 and interferon-related gene ISG15 and the NF-κB downstream genes IL-6 and TNF-α induced by HCMV early infection." (PMID 29194430, 2017). "However, in the murine system when the ISGylation machinery is overexpressed prior to infection or when USP18-mutant cells are infected, where high levels of ISG15 conjugation are observed, viral titers decrease by more than one log." (PMID 29077752, 2017). "On the other hand, PRRSV could inhibit IFN-mediated JAK-STAT signaling pathways to interrupt ISG transcription; for example, ISG15, ISG56, CCL2, MX1, OAS2, and RNaseL of PAMs were significantly downregulated after infection with the PRRSV strain VR2385." (PMID 27182980, 2016). "RNA interference of UBE1L (E1), UbcH8 (E2), Herc5 (E3), and UBP43 (ISG15 protease) revealed that ISGylation inhibits HCMV growth by downregulating viral gene expression and virion release in a manner that is more prominent at low multiplicity of infection." (PMID 27564865, 2016). "One could have predicted an even better rescue of both the ISG expression and infection phenotypes by ISG15ΔGG, since the latter should be more readily accessible to mediate USP18 stability than the conjugation-competent form of ISG15." (PMID 27193971, 2016). "We also compared the levels of ISG15 and ISG15 conjugates in HCMV, UV-HCMV, and CR208 infection." (PMID 27564865, 2016). "Twenty four host proteins (17 in the cytosol and seven in the nucleus) are up-regulated ≥1.5-fold by T3D infection but not by T1L infection, and four of these proteins (Mx1, ISG15, IFIT1, and STAT1) are up-regulated >3.5-fold by T3D." (PMID 25905045, 2015). "One possible reason for this discrepancy is that IFN-alpha in plasma becomes undetectable by ELISA in the chronic phase of the infection and is therefore less sensitive for determining the interferon response than measuring ISG like MX1 as in our work or ISG15." (PMID 26554913, 2015).
infection (continued). "The in vitro susceptibility is clearly conjugation-dependent and we have preliminary data suggesting that the conjugation incompetent mutant of ISG15 does not protect cells from infection (data not shown)." (PMID 26259872, 2015). "LV-shDUSP1 infection enhanced mRNA expression of myxovirus resistance protein A (MxA), 2'-5'-oligoadenylate synthetase 1 (OAS1), ISG15 ubiquitin-like modifier (ISG15), chemokine C-X-C motif ligand 10 (CXCL10), and USP18 relative to those in LV-cont-infected cells (P < 0.05)." (PMID 25798824, 2015). "The selected targets included genes that were differentially expressed in both gt1‐ and gt3‐infected samples versus controls (CXCL9, IFIT1, ISG15 and RSAD2), as well as genes that were differentially regulated only in gt1 infection (USP18) or gt3 infection (IDO1)." (PMID 25800823, 2015). "Electro-mobility Shift Assays (EMSA) were used to test whether IRF3(5D) from cells containing both IRF3(5D) and PLpro was able to bind to the ISG15 or OAS1b promoter, both of which are bound by IRF3 during infection." (PMID 25481026, 2014). "However, in the infected peritoneal macrophages, a higher percentage of ISG15−/− cells survived to the infection, at each multiplicity of infection (MOI) analyzed, in comparison to the results in ISG15+/+ macrophages." (PMID 24137104, 2013). "Both MEFs and dendritic cells (not shown) VACV-infected were unaffected by the lack of ISG15 in the course of infection." (PMID 24137104, 2013). "Whereas WT macrophages became apoptotic and die after infection, in ISG15−/− macrophages, in which VACV infection is also abortive, no apoptosis was observed, as evidenced by the absence of PARP cleavage and CPE." (PMID 24137104, 2013). "Rapid induction of ISG15 through this pathway has a dual function: (i) it controls the RIG-I pathway by interfering with RIG-I ubiquitination, hence limiting IFN induction, and (ii) it maintains PKR phosphorylation later in infection." (PMID 23202496, 2012). "While analyzing the regulation of IFN induction pathway by ISG15 in JFH1-infected Huh7.25/CD81 cells, we noticed that the expression of ISG15, as well as ISG56, another IRF3‐responsive ISG, increased in response to JFH1 infection in the Huh7.25/CD81 cells." (PMID 23202496, 2012). "Surprisingly, the mechanism of action by which ISG15 limits infection is independent of UbE1L mediated conjugation, as UbE1L−/− mice displayed no phenotypic differences as compared to WT animals." (PMID 22028657, 2011). "In contrast, a dramatic increase in lethality was observed in neonatal mice lacking ISG15, with greater than 70% of the ISG15−/− mice succumbing to infection within 3 days, and 100% of the mice dying by day 9 post-infection." (PMID 22028657, 2011). "By 12 days of age the ISG15−/− mice still showed clinical signs of disease, with a dramatic decrease in weight gain as compared to the WT controls (data not shown), but by this age only 20% of the ISG15−/− mice succumbed to the infection." (PMID 22028657, 2011). "This excludes any indirect effect of infection on ISGylation through an effect on ISG15 expression or stability." (PMID 22163042, 2011). "Western blot analysis on skin/muscle from the site of infection, as well as serum, was used to confirm that UbE1L−/− mice generated no ISG15 conjugates during CHIKV infection, whereas WT mice showed robust conjugate formation." (PMID 22028657, 2011). "Infection of ISG15−/− mice with a mutant virus lacking this ISG15 antagonist did result in increased lethality as compared to WT mice, providing another model in which ISG15 played a role." (PMID 21994614, 2010). "In these studies, the role of SOCS1 and SOCS3 negative regulation of the type I IFN response and ISG15 expression were evaluated after infection of MLE-15 cells with RSV or RSV mutant viruses lacking the G gene, or having NS1 and NS2 gene deletions." (PMID 18851747, 2008).
infection (continued). "The mutant VVΔE3L virus that was able to replicate in ISG15−/− MEFs did not replicate in ISG15 KO mice, but surprisingly infection with VVΔE3L provokes sickness and mortality only in ISG15−/− mice." (PMID 18604270, 2008). "Since the inflammatory response might explain the rapid signs of illness in VVΔE3L infected ISG15 KO mice, we measured serum cytokine levels (IL-6, TNF-α, IL-10, MCP-1, IFN-γ, and IL-12 p 70) at early times post infection." (PMID 18604270, 2008). "The studies center on SOCS1 and SOCS3 negative regulation of the type I IFN response and ISG15 expression following infection with RSV or RSV mutant viruses lacking the G gene, or NS1 and NS2 gene deletions." (PMID 18851747, 2008). "We find that in the absence of ISG15, infection with VVΔE3L produces an increase of IL-6 that correlates with short-term morbidity and complications that include pulmonary function abnormalities." (PMID 18604270, 2008). "To find out whether a decrease of virus load observed in the presence of Iristatin results in a decrease of IFN or ISGs, we measured gene expression of IFN-β and four interferon-stimulated genes, namely ISG15, CXCL-10, OASL2, and IFIT2 in skin tissue two and 5 days after Hypr infection." (PMID 39821815, 2025). "Moreover, whereas ubiquitin, Nedd8, and SUMO are constitutively expressed in cells, ISG15 is strongly induced by type I interferons (IFN-α and IFN-β) in response to infections (viral, bacterial, and parasite), polyinosinic:polycytidylic acid (poly I:C), or lipopolysaccharide." (PMID 40631552, 2025). "Following RSV-L19 infection (MOI = 10) of sh-ARCN1-RAW264.7 cells for 12 h, RT-qPCR analysis revealed significantly increased mRNA levels of Ifnb1 and interferon-stimulated genes Isg15 and Ifit1 compared to sh-NC-RAW264.7 controls, suggesting that ARCN1 suppresses RSV-induced IFN-β signaling." (PMID 41343552, 2025). "The infection with viral strains that were only defective in the expression of MHC immune evasion genes US2, US3, US6, and US11 still showed some reduction in the steady-state levels of ISGs Mx1 and ISG15, but also showed slightly elevated levels of IFIT3, compared to the wt-control virus." (PMID 40143353, 2025). "The ability to differentiate between positive and negative samples with 100% accuracy using IFI6, IFI27, or ISG15 as predictors highlights the significant alteration of these genes following infection and their potential as reliable indicators of EBOV presence in NHPs." (PMID 39282474, 2024). "Interestingly, in the infection situation studied here, ISG15 transcription was induced even in the absence of IFNAR signaling." (PMID 39345209, 2024). "The infection, when performed by fish immersion in the viral suspension induces the expression of il1b from 24 to 48 hpi in the absence of induction of type-I ifn and isg15 gene expression." (PMID 39102417, 2024). "Given the difference in infectious particles and RNA between CHIKV-IOL and CHIKV-181/25, it aligns that CHIKV-181/25 infection produces a marked increase in ISG15 at 24 hours, while the non-replicating CHIKV-IOL does not significantly induce ISG15 above the control." (PMID 39314478, 2024). "Notably, the infection-induced proteotoxic stress response was also among the highly enriched pathways in upregulated genes from IAV-infected DTC, HBTE-, and A549 cells, while network analysis reiterated the ISG15 antiviral response." (PMID 38590437, 2024). "By contrast, the overexpression of circYthdc2 or Linear-FLAG-Ythdc2-170aa both could significantly inhibit the expression levels of interferon IFN1, inflammatory cytokines (TNF-α), and antiviral genes such as myxovirus resistance protein 1 (Mx1), ISG15, and Viperin after SCRV infection." (PMID 38361078, 2024). "In contrast to ISG15 null cells, we did not observe differences between WT and HERC5-deficient cells when we evaluated both foci area and number of infected cells per foci following infection with DV." (PMID 38384473, 2024).
infection (continued). "PHEV significantly upregulated ISG15 expression (>1.5 log2FC) at all three time points, and it appears ISG15 does interact with HERC5, IFIT1, PKR, TRIM25, STAT1, and USP18, as their expression was also enhanced (>1.0 log2FC) at various timepoints during ALI-PRECs infection." (PMID 38932231, 2024). "SARS-CoV-2-Δ8 infection showed a trend of increasing IFN signaling (IFNλ3, interferon-stimulated gene [ISG15], and MX1, P values 0.4337, 0.1126, and 0.2285, respectively) as compared to WT at 3 dpi, while reducing IFN-stimulated gene levels (IFNλ3, ISG15, IFIT1, OAS1, and XAF1) at 6 dpi." (PMID 37623322, 2023). "Finally, infection of MIA PaCa-2 with either virus resulted in a minor downregulation of ISG15 and no change in mRNA expression for ISG54." (PMID 36851497, 2023). "RT-qPCR did not reveal significant differences in the amount of TMEV RNA as well as Ifnb1, Isg15, Eif2ak1 (PKR), Tnfa, Il1a, Il1b, Il6, Il10, Il12 (p40) and Ifng transcript numbers in the brain of Asc−/− and Casp1−/− mice and their respective wild type littermates at 4 days after TMEV infection." (PMID 37414913, 2023). "Notably, we again observed that WY14643 reduced the transcripts of Ifnb, Isg15, Isg20, and Cxcl10 without infection, though the effect was not significant for Isg20 in Ppara−/− cells." (PMID 36715509, 2023). "Progression of infection results in damage to the host epithelium, which responds with an expression signature of type-I Interferon (IFN) signalling dominated by Interferon-stimulated gene 15 (Isg15), an alarmin that initiates immune and tissue repair responses." (PMID 35365634, 2022). "Infection-induced gene expression levels of inflammatory cytokines such as Il6 and Tnf, type I (Ifna4 and Ifnb), and type III IFNs (Ifnl2/3) as well as ISGs such as Mx1, Isg15, and Stat1 peaked simultaneously with peak viral loads on day 2 p.i. in lungs and upper airways." (PMID 36129445, 2022). "To test whether ISG15 is involved in type I IFN-mediated antiviral innate immune response in vivo, we first compared the body weight between WT and ISG15-/- mice after infection with PRV with or without IFNα treatment." (PMID 36146669, 2022). "Other ISGs regulated by rDEN2Δ30 infection such as ISG15 and IFI27 have not been well-documented in natural infection though may play a role in controlling viral replication among other functions." (PMID 34031380, 2021). "Thus, we next measured expression of several ISGs, including Isg15, Ifit1 and Mx1, over the same time course in BMDMs in addition to RAW 264.7 macrophages and observed significant induction of these genes 4h post-infection with higher induction at 8h in both cell types." (PMID 34473814, 2021). "In addition, the expression of endogenous ISG15 was also efficiently suppressed by infection with both NH/P68 and Arm/07/CBM/c2 ASFV strains in COS-1 cells treated with IFN-I, both the unconjugated (15 kDa) and a conjugated (35 kDa) form of ISG15." (PMID 34512601, 2021). "At the transcriptome level, the high expression levels of viral sensors MDA5 (IFIH1), R1G-1 (DDX58), and ISGS (ISG15, Mx1, Mx2, RSAD2, IFIT3, and IFIT5) and transcription factors like IRF-7 and STAT-1 that induce ISG expression were found in lymphocytes during virulent PPRV infection." (PMID 34631844, 2021). "We conclude that ISG15 connects the ATG and IFN-γ-dependent control of T. gondii infection in human cells, suggesting that ISG15 may also contribute to the control of other infections where IFN-γ-induced autophagy plays an important role (75, –, 77)." (PMID 33024031, 2020). "Furthermore, a comparison of sites identified by quantitative diglycine enrichment between Isg15−/− and wild-type animals prior to infection shows no significantly regulated sites." (PMID 31772204, 2019).